NDUFA12 (NADH:ubiquinone oxidoreductase subunit A12)
Description:
Accessory subunit of the mitochondrial membrane respiratory chain NADH dehydrogenase (Complex I), that is believed not to be involved in catalysis. Complex I functions in the transfer of electrons from NADH to the respiratory chain. The immediate electron acceptor for the enzyme is believed to be ubiquinone.
Synonyms: DAP13; B17.2; MC1DN23
Tractability: Small molecule: an approved drug acts on it; a structure with a bound ligand is known. Antibody: UniProt places it where antibodies can reach, with medium confidence. PROTAC: ubiquitination databases record sites on it; its protein half-life has been measured.
Gene: Protein-coding gene on chromosome 12 (94,895,297 to 95,003,748, reverse strand). Ensembl gene ENSG00000184752.
Subcellular location: Mitochondrion inner membrane
Subcellular location (Human Protein Atlas): Mitochondria; Cytosol
Pathways (Reactome):
Metabolism: Complex I biogenesis; Respiratory electron transport
Gene Ontology:
Molecular function: protein binding; NADH dehydrogenase (ubiquinone) activity
Biological process: mitochondrial ATP synthesis coupled electron transport; aerobic respiration; proton motive force-driven mitochondrial ATP synthesis; proton transmembrane transport
Cellular component: mitochondrial inner membrane; mitochondrion; respiratory chain complex I; membrane
Genetic constraint (gnomAD): Loss-of-function variants: 16 observed, 20.45 expected, observed/expected ratio (o/e) 0.78, 90% interval 0.53 to 1.19. The upper end of that interval is the gene's LOEUF score, 1.19, which puts it in group 5 of 6, group 1 being the genes least tolerant of losing a copy. Missense variants: 191 observed, 194.19 expected, observed/expected ratio (o/e) 0.98, 90% interval 0.87 to 1.11. Synonymous variants: 72 observed, 68.26 expected, observed/expected ratio (o/e) 1.05, 90% interval 0.87 to 1.28.
Gene-disease validity (ClinGen):
ClinGen rates the evidence that NDUFA12 causes each of these diseases.
mitochondrial disease (autosomal recessive): Definitive.
Leigh syndrome (autosomal recessive): Limited. A progressive neurological disease defined by specific neuropathological features associating brainstem and basal ganglia lesions.
Homologues: Orthologues: chimpanzee NDUFA12 (100% identical), macaque NDUFA12 (94% identical), rabbit NDUFA12 (92% identical), guinea pig NDUFA12 (92% identical), dog NDUFA12 (91% identical), rat Ndufa12 (90% identical), mouse Ndufa12 (89% identical), zebrafish ndufa12 (63% identical), tropical clawed frog ndufa12 (61% identical), Caenorhabditis elegans ndua-12 (39% identical), Drosophila melanogaster ND-B17.2 (37% identical).
Diseases named in the same sentence as NDUFA12 in open-access papers:
NDUFA12 is named in the same sentence as 28 diseases in open-access papers, as found by Europe PMC text mining. Sharing a sentence is not in itself a finding about the gene and the disease. The quoted sentences say what the papers report.
Leigh syndrome (6 papers, 2018 to 2025). "NDUFA12 impairment is strongly associated with Leigh syndrome in humans, a paediatric mitochondrial disorder characterized by brain-specific anomalies and early death for which no fully compensatory mechanisms are known." (PMID 39174672, 2024). "The first reported case of NDUFA12‐related mitochondrial disease was a Pakistani child with Leigh syndrome (LS) carrying a homozygous nonsense variant." (PMID 35141356, 2022). "In line with previously reported complex I deficient patients, we found that defects in NDUFS7, NDUFA12, and NDUFAF5 caused Leigh-syndrome or a Leigh-like-phenotype." (PMID 30369941, 2018). "Defects in NDUFS7, NDUFA12 and NDUFAF5 caused Leigh-syndrome or a Leigh-like-phenotype." (PMID 30369941, 2018).
Dystonia (2 papers, 2022 to 2025). An abnormally increased muscular tone that causes fixed abnormal postures. "It confirms NDUFA12 variants should be included in the diagnostic workup of Leigh/Leigh‐like syndromes – particularly with dystonia – as well as isolated optic atrophy." (PMID 35141356, 2022). "As dystonia was always associated with MRI evidence of BG damage in our series and previous cases, a secondary etiology (structural damage caused by mitochondrial dysfunction) most likely explains its occurrence in NDUFA12‐related LS/LLS." (PMID 35141356, 2022). "It supports the inclusion of NDUFA12 variants in the diagnostic workup of not only LS/LLS, particularly when dystonia is the prominent motor manifestation, but also isolated OA." (PMID 35141356, 2022).
Cognitive impairment (1 paper, 2024). Abnormal cognition is characterized by deficits in thinking, reasoning, or remembering. "In participants with cognitive impairment, the expression levels of KEGG:M00146’s NDUFA2, NDUFA3, NDUFA4, NDUFA6, NDUFA7, NDUFA10, and NDUFA12 increased, but the expression levels of NDUFA5, NDUFA4L2, and NDUFAB1 marginally decreased." (PMID 38542318, 2024).
diabetic cardiomyopathy (1 paper, 2022). Diabetic cardiomyopathy is a disorder of the heart muscle in people with diabetes. "The pathways of neurodegeneration/multiple diseases and diabetic cardiomyopathy were also significant pathways and shared altered proteins such as Atp2a32, Uqcr10, Ndufa12, Vdac1, and Vdac3." (PMID 35565902, 2022).
glioblastoma (1 paper, 2024). The most malignant astrocytic tumor (WHO grade IV). "The binding of 7MeERT and Ertredin to NDUFA12 in glioblastoma was further supported by the inhibition of the oxygen consumption rate." (PMID 39334963, 2024).
schizophrenia (1 paper, 2018). A major psychotic disorder characterized by abnormalities in the perception or expression of reality. "Additionally, the intra-module hub gene from a yellow module with the highest value of connectivity was a schizophrenia-associated gene known as HINT1, and two of the top five connected intra-module hubs in module yellow were MRPS18C and NDUFA12, which are implicated in the function of mitochondria." (PMID 29958387, 2018).
type 2 diabetes (1 paper, 2023). "NDUFA12 is a small hydrophobic accessory subunit of Complex I, identified as a novel binding partner of the serine/threonine p21-activated kinase that increases susceptibility to type 2 diabetes." (PMID 37168668, 2023).
cancer (4 papers, 2015 to 2024). A tumor composed of atypical neoplastic, often pleomorphic cells that invade other tissues. "Furthermore, NDUFA12 has emerged as a target protein for the natural small molecule Ertredin, which has demonstrated efficacy in inhibiting the growth of cancer cells harboring EGFRvIII mutations, associated with anti-tumor activity." (PMID 39585490, 2024). "Exploring the role of NDUFA12 in other cancer types and understanding how mitochondrial metabolism contributes to cancer progression will be important areas for future research." (PMID 39334963, 2024). "Given that NDUFA12 is involved in the electron transfer process and is essential for energy metabolism, it has become a potential therapeutic target in cancers that rely on mitochondrial respiration." (PMID 39334963, 2024). "Collectively, these results suggest that both 7MeERT and Ertredin inhibit energy metabolism and proliferation in various human cancer cells by targeting NDUFA12." (PMID 39334963, 2024). "The one-amino acid deletion in NDUFA12 was instead present also in the non-cancer tissue surrounding the lesion." (PMID 25880213, 2015). "By binding to NDUFA12, Ertredin may affect the energy metabolism of cancer cells, thereby contributing to its antiproliferative activity." (PMID 39334963, 2024).
mitochondrial disease (4 papers, 2020 to 2024). "Our case series expands phenotype–genotype correlations in NDUFA12‐associated mitochondrial disease, providing evidence of intra‐ and inter‐familial clinical heterogeneity for the same variant." (PMID 35141356, 2022). "In conclusion, our case series expands the phenotype–genotype spectrum of NDUFA12‐associated mitochondrial disease and provides evidence of inter‐ and intra‐familial clinical heterogeneity associated with the same variant." (PMID 35141356, 2022). "Our series expands the age of onset of NDUFA12‐related mitochondrial disease to as late as 28 years." (PMID 35141356, 2022). "Many mitochondrial disease-related altered proteins also formed part of the energy network (DLD, NDUFA4, NDUFB5, NDUFB6, NDUFB9, NDUFS1, NDUFA12 and UQCRB) and belong to respiratory electron transport with the exception of DLD, which belongs to the TCA cycle." (PMID 34576238, 2021).
infection (3 papers, 2020 to 2024). The state of being infected such as from the introduction of a foreign agent such as serum, vaccine, antigenic substance or organism. "Moreover, genes involved in active metabolism like COX7A2, NDUFB6 (ILC2), NDUFA12 (ILCP), ACSL1 (NK CD16high), and DNAJA4 (NK CD56high) were upregulated in HIV-infected children, suggesting active metabolism in these subsets in response to infection." (PMID 32937142, 2020).
neurodegenerative disease (1 paper, 2025). A disorder of the central nervous system characterized by gradual and progressive loss of neural tissue and neurologic function. "The mitochondrial dysfunction in the neurodegenerative diseases cluster (Cluster 4) comprises 95 genes, including several key mitochondrial protein genes acting as pivotal hub genes, such as Sdhb, Ndufa4, Ndufb4c, Ndufb4b, Ndufv3, Ndufa9, Ndufc1, Ndufs5, Ndufb4, Ndufa12, Ndufa11, and Ndufb1." (PMID 41294802, 2025).
NDUFA12 also shares sentences with these, for which no sentence is quoted: Alzheimer disease (3 papers); optic atrophy (2); Atrophy (1); brain diseases (1); cerebellar ataxia (1); cervical cancer (1); cognitive decline (1); colon cancer (1); Huntington disease (1); liver cancer (1); neurological diseases (1); Parkinson disease (1); retinal degeneration (1); spinal cord injury (1); thyroid cancer (1); tumor (1); virus infection (1).